ENSG00000167774 (novel transcript)
Gene: Protein-coding gene on chromosome 19 (8,308,283 to 8,321,379, reverse strand). Ensembl gene ENSG00000167774.
Genetic constraint (gnomAD): Missense variants: 155 observed, 134.29 expected, observed/expected ratio (o/e) 1.15, 90% interval 1.01 to 1.32. Synonymous variants: 70 observed, 54.72 expected, observed/expected ratio (o/e) 1.28, 90% interval 1.05 to 1.56.